MMP2 (matrix metallopeptidase 2)
Diseases named in the same sentence as MMP2 in open-access papers (continued):
Sharing a sentence is not in itself a finding about the gene and the disease.
pelvic organ prolapse (4 papers, 2024 to 2025). Abnormal descent of a pelvic organ resulting in the protrusion of the organ beyond its normal anatomical confines. "This study aimed to elucidate the roles of junctional adhesion molecule 2 (JAM‐2), collagen I and matrix metalloproteinase 2 (MMP‐2) in the pathogenesis of pelvic organ prolapse (POP) and explore their potential as diagnostic markers." (PMID 40159633, 2025). "Importantly, our study demonstrates the significant diagnostic potential of JAM‐2, Collagen I and MMP‐2 for pelvic organ prolapse (POP)." (PMID 40159633, 2025). "To compare the levels of IL‐6, TNF‐α and MMP2 in vaginal wall tissues between patients diagnosed with pelvic organ prolapse and a control group, we gathered a total of 80 vaginal wall tissue samples." (PMID 38898783, 2024). "Our findings revealed a significant elevation in interleukin (IL)‐6 and TNF‐α, and matrix metalloproteinase‐2 (MMP2) levels in the vaginal wall tissues of patients with pelvic organ prolapse (POP) compared with the control group." (PMID 38898783, 2024). "According to unvariable analyses, statistically significant association was noted between positive immunoreactivity to MMP-1, MMP-2, and MMP-9 in the round ligaments and the occurrence of pelvic organ prolapse." (PMID 40607267, 2025). "Vaginal distention in Fbln-5-/- mice has been shown to induce activity of proteases (MMP2 and MMP9) in vaginal tissue, but increased production of other SASP cytokines unique to pelvic organ prolapse in mice has not yet been completely elucidated." (PMID 39331015, 2024).
Peptic ulcer (4 papers, 2023 to 2025). The term peptic ulcer refers to acid peptic injury of the digestive tract, resulting in mucosal break reaching the submucosa. "It seems that peptic ulcer disease caused by infection with H. pylori increases the MMP-2/TIMP-1 ratio in patients with peptic ulcers." (PMID 37605137, 2023). "This study aimed to evaluate the ratios of matrix metalloproteinase-2 (MMP-2) to tissue inhibitor of metalloproteinase-1 (TIMP-1) in patients with peptic ulcers that are sensitive or resistant to H. pylori treatment and compare them with healthy individuals." (PMID 37605137, 2023). "In patients with H. pylori-induced peptic ulcers, the MMP-2/TIMP-1 ratio was significantly higher than the healthy controls (P < 0.05)." (PMID 37605137, 2023).
prostate (4 papers, 2014 to 2023). "Some anti-angiogenesis related genes were essentially down-regulated in PC3 cells, i.e. MMP2, TNF-alpha, CCL11 and the potent pro-angiogenic factor IGF1 (9 fold down-regulation) which is deeply involved in prostate carcinogenesis and identified as autocrine proliferation stimulus for hPCa cells." (PMID 24681516, 2014).
schwannoma (4 papers, 2012 to 2020). A benign, usually encapsulated slow growing tumor composed of Schwann cells. "To investigate whether the signaling pathway through P2Y receptors is implicated in Schwannoma cell migration and MMP-2 activation, and given that P2Y receptors have been reported to induce MAPK activity, we determined whether the P2Y-MAPK pathway mediated UTP-induced migration in Schwann cell line." (PMID 24905332, 2014). "For example, the promoting effect of uridine 5′-triphosphate on Schwannoma cell migration was through the activation of MMP2." (PMID 30425652, 2018). "For the first time, we report that UTP stimulates in vitro Schwannoma cell migration and wound repair through a MMP-2-dependent mechanism via P2Y2 receptors and MAPK pathway activation." (PMID 24905332, 2014). "In conclusion, our findings show that treatment with UTP stimulates in vitro Schwannoma cell migration and wound repair through a MMP-2-dependent mechanism via P2Y2 receptors and MAPK pathway activation." (PMID 24905332, 2014). "One possible explanation for late MAPK phosphorylation is that active MMP-2 in the extracellular space cleaves a membrane-anchored growth factor on Schwannoma cells." (PMID 24905332, 2014). "Our data suggests that the initial transient phase of MAPK activation in Schwannoma cells is mediated by P2Y receptors, whereas the late sustained phosphorylation is also mediated by MMP-2 activation." (PMID 24905332, 2014). "Finally, to evaluate the role of activated MMP-2 in Schwannoma cell wound repair, a short hairpin RNA (shRNA) directed against the rat MMP-2 gene (shMMP-2) was developed." (PMID 24905332, 2014). "The present study aimed to determine the effect of extracellular uridine 5′-triphosphate (UTP) on Schwannoma cell migration and wound repair and to establish whether MMP-2 is involved in this effect." (PMID 24905332, 2014). "Nevertheless, the relationship between MMP-2 activation and late MAPK phosphorylation observed in our Schwannoma cell model merits further investigation in primary Schwann cell culture." (PMID 24905332, 2014). "We found that UTP treatment induced Schwannoma cell migration through activation of P2Y2 receptors and through the increase of extracellular matrix metalloproteinase-2 (MMP-2) activation and expression." (PMID 24905332, 2014). "Thus, the cleavage of a growth factor (NRG1 type III) by MMP-2 and the subsequent phosphorylation of the ErbB transmembrane tyrosine kinase receptor could explain the late MAPK phosphorylation observed in Schwannoma cells after UTP treatment." (PMID 24905332, 2014). "Nevertheless, MMP-2 was not one of the proteases with dysregulated expression from our meta-analysis of the genome-wide transcriptional microarray data, and MMP-2 mRNA levels were not significantly upregulated in either human VS cultures or schwannoma cells in vitro." (PMID 32848608, 2020).
small cell lung carcinoma (4 papers, 2020 to 2023). Small cell lung cancer (SCLC) is a highly aggressive malignant neoplasm, accounting for 10-15% of lung cancer cases, characterized byrapid growth, and early metastasis. "MMP2, matrix metalloproteinase 2; SCLC, small cell lung cancer." (PMID 33115469, 2020).
spinal cord injury (4 papers, 2017 to 2025). Penetrating and non-penetrating injuries to the spinal cord resulting from traumatic external forces (e.g., WOUNDS, GUNSHOT; WHIPLASH INJURIES; etc.). "Spinal cord injuries induce the release of inflammatory mediators, e.g., IL-6, IL-8, IL-10, matrix metalloproteinase-2 (MMP-2), and MMP-9." (PMID 40717731, 2025). "Inhibiting the expression and activation of both metal matrix proteinase (MMP)-2 and MMP-9 after spinal cord injury (SCI) and the mRNA expressions of TNF-α, IL-1β, COX-2, and iNOS." (PMID 27951737, 2017). "Further mechanisms with relevance for neurologic disorders are the downregulation of matrix metalloproteinase-2 (MMP-2), MMP-9 and interleukin (IL-6) which, in an animal experiment of spinal cord injury (SCI), inversely correlated with the spinal water content, thus promoting recovery." (PMID 40731157, 2025).
ulcerative colitis (4 papers, 2011 to 2023). An inflammatory bowel disease involving the mucosal surface of the large intestine and rectum. "In a model of dextran sulfate sodium (DSS)-induced ulcerative colitis, the DSS-induced increase in the enzymatic activity of MMP-2, -7, and -9 was diminished by AUR therapy." (PMID 37496822, 2023). "The expression and activities of MMP2 and MMP9 were increased in different models of experimental colitis, moreover, MMPs were overexpressed in the inflamed tissue of patients with ulcerative colitis." (PMID 28797051, 2017).
uterine leiomyosarcoma (4 papers, 2013 to 2024). "Research has revealed a beneficial link between the co-expression of TEM1 and MMP-2 in uterine leiomyosarcoma specimens." (PMID 38410101, 2024). "Using short-interfering RNA (siRNA), frizzled-6 was silenced in the SK-LMS-1 uterine leiomyosarcoma cell line, thus significantly inhibiting cellular invasion, wound healing, and matrix metalloproteinase-2 (MMP-2) activity." (PMID 37173887, 2023). "TEM1 and MMP-2 were expressed in 92% (n = 23) and 88% (n = 22) of uterine leiomyosarcoma specimens, respectively." (PMID 36639546, 2023). "Both TEM1 and MMP-2 were highly expressed in 100% (n = 17) of high stage (III-IV) uterine leiomyosarcoma specimens." (PMID 36639546, 2023). "Our analysis revealed a high expression pattern of TEM1 and MMP-2 in uterine leiomyosarcoma with percentage of 92% (23/25) and 88% (22/24)." (PMID 36639546, 2023). "Our analysis revealed that TEM1 and MMP-2 were expressed in 92% (23 positive) and 88% (22 positive) of the 25 uterine leiomyosarcoma tissues, respectively." (PMID 36639546, 2023). "Altogether, these results indicate that TEM1 and MMP-2 were co-expressed in uterine leiomyosarcoma tissues, especially high-grade lesions, suggesting poor prognosis in uterine leiomyosarcoma patients." (PMID 36639546, 2023). "In addition, TEM1 expression was positively correlated with MMP-2 expression in uterine leiomyosarcoma." (PMID 36639546, 2023). "The expression of TEM1 and MMP-2 and their correlation with uterine leiomyosarcoma was explored." (PMID 36639546, 2023). "TEM1 was co-expressed and positively correlated with MMP-2 in uterine leiomyosarcoma specimens." (PMID 36639546, 2023). "Uterine leiomyosarcoma showed strong bands corresponding to inactive and active MMP-9 and a faint band corresponding to MMP-9 dimer induced with PMA treatment, but no MMP-2 band." (PMID 23661254, 2013). "Furthermore, we found that TEM1 and MMP-2 expression was positively correlated with tumor stage, implying that MMP-2, rather than MMP-9, might participate in TEM1-mediated tumorigenesis of uterine leiomyosarcoma." (PMID 36639546, 2023). "MMP-2, but not MMP-9, might work together with TEM1 in uterine leiomyosarcoma progression." (PMID 36639546, 2023).
abortion (3 papers, 2022 to 2025). the ending of pregnancy by removing a fetus or embryo before it can survive outside the uterus. "In Chinese women, the MMP2 rs243865 T allele is closely associated with the risk of recurrent spontaneous abortion (RSA)." (PMID 40151207, 2025). "Elevated levels of MMP2 and TIMP2 have been observed in patients with spontaneous abortion." (PMID 40151207, 2025). "Supporting this hypothesis, a previous study documented that overexpression of TNF-α, reduce MMP-2 and MMP-9, while an aggravation of the severity of abortion in rats further prompted TNF-α expression that sequentially decreased MMP-2 and MMP-9 levels." (PMID 35622593, 2022).
acute lung injury (3 papers, 2014 to 2022). A condition of lung damage that is characterized by bilateral pulmonary infiltrates (pulmonary edema) rich in neutrophils, and in the absence of clinical heart failure. "Acute lung injury (ALI) is one of the fatal outcomes after exposure to high levels of hydrogen sulfide (H2S), and the matrix metalloproteinases (MMPs) especially MMP-2 and MMP-9 are believed to be involved in the development of ALI by degrading the extracellular matrix (ECM) of blood-air barrier." (PMID 24722316, 2014).
AIDS (3 papers, 2011 to 2022). A syndrome resulting from the acquired deficiency of cellular immunity caused by the human immunodeficiency virus (HIV). "However, in AIDS patients, the tat (Trans-Activator of Transcription) protein encoded by the human immunodeficiency virus 1 increases MMP-2 expression in AIDS-KS lesions and MMP-2 plasma levels, suggesting that tat could play a role in the higher aggressiveness of KS in AIDS patients." (PMID 35626397, 2022). "In conclusion, our study explored using the PI, indinavir, against two potential extracellular binding targets (MMP-2 and α7-nAchR) for use in cancer treatment, and measured their binding values against that of HIV-1 protease, an intracellular target for indinavir in HIV/AIDS treatment." (PMID 31687607, 2019). "Future studies could attempt to develop a structural analog of indinavir with a much lower or nonexistent binding affinity to MMP-2 and the α7-nAchR, which could overcome these hurdles and become more effective in reaching and acting on HIV-1 protease in HIV/AIDS affected individuals." (PMID 31687607, 2019).
alcohol (3 papers, 2015 to 2025). "Additionally, the identification of the clinically validated biomarker of astrocyte activation, GFAP, and the protein Matrix Metalloproteinase 2 (MMP2) associated with BBB breakdown, in Dep mice supports the hypothesis that BBB disruption and immune dysregulation is unique to alcohol dependence." (PMID 41292811, 2025).
anaplastic thyroid cancer (3 papers, 2012 to 2018). "In anaplastic thyroid cancer cells, leptin induced the expression of MMP2, and MMP9 which are involved in the invasion of cancer cells." (PMID 27050378, 2016). "In summary, leptin in anaplastic thyroid cancer cells not only increased expression of MMP2, MMP9 and VEGF in the current studies, supporting angiogenesis, but also induced cancer cell invasiveness and reduced adhesion." (PMID 27050378, 2016). "PLK1 siRNA suppressed the cell invasion of undifferentiated thyroid carcinoma, and CD44v6, MMP-2 and MMP-9 contributed to the regulation of cell invasion of undifferentiated thyroid carcinoma via PLK1." (PMID 23226764, 2012). "OB3 induced only MMP2 significantly and MMP9 marginally in anaplastic thyroid cancer cells." (PMID 27050378, 2016).
angiomyolipoma (3 papers, 2018 to 2023). A neoplasm with perivascular epithelioid cell differentiation often associated with tuberous sclerosis. "Angiomyolipoma cells express mRNA coding for SDF-1α and 17-β-estradiol receptors and secrete both the metalloproteases principally involved in malignant phenotype acquisition, i.e. MMP-2 and MMP-9." (PMID 29920561, 2018).
Arrhythmia (3 papers, 2020 to 2022). Any cardiac rhythm other than the normal sinus rhythm. "In this multi-ethnic study cohort, we found that RANTES is associated with sex, EMMPRIN is associated with a history of arrhythmia and LDL levels, MMP-2 with age, and MMP-9 with ethnicity and hs-CRP levels." (PMID 36555898, 2022).
benign breast tumors (3 papers, 2019 to 2023). "Moreover, MMP-2 levels were significantly lower in stage I BC as compared with benign breast tumor group." (PMID 33371324, 2020). "In particular, MMP-11, but also MMP-2, and MMP-9 were higher in BC when compared with benign breast tumors." (PMID 37798646, 2023). "In this study, there was a higher mRNA expression of MMP-2 and MMP-9 in BC patients compared to benign breast tumors, but no statistical significance." (PMID 37798646, 2023).
benign prostatic hyperplasia (3 papers, 2008 to 2022). A non-cancerous nodular enlargement of the prostate gland. "Correspondingly, several other studies have reported an increased expression of hsa-miR-200b-3p in PCa compared with that in benign prostatic hyperplasias, as well as a positive correlation with TIMP4, which is an inhibitor of MMP2." (PMID 36232996, 2022).
bone metastasis (3 papers, 2012 to 2022). Transfer of a neoplasm from its primary site to bones. "Higher MMP-2 expression in CTCs and DTCs of patients with bone metastasis." (PMID 35669415, 2022).
carotid atherosclerosis (3 papers, 2016 to 2024). A thickening and loss of elasticity of the walls of carotid arteries that occur with formation of atherosclerotic plaques. "Indeed, we reported the association of the MMP-2/TIMP-2 system with carotid atherosclerosis and cardiovascular risk in patients with severe CKD on dialysotherapy." (PMID 38610612, 2024). "Our previous studies demonstrated increased circulating MMP-2 and TIMP-2 levels in patients with CKD, which was associated with hypercoagulability, oxidative stress, inflammation, carotid atherosclerosis, and cardiovascular risk." (PMID 38610612, 2024).
cerebrovascular disease (3 papers, 2013 to 2018). "During the past years different SNPs within the MMP-2 gene and their association with cerebrovascular diseases were studied." (PMID 29435135, 2018). "In cerebrovascular diseases, the imbalance of MMP-2 and TIMP-2 can cause vascular remodeling and dysfunction, cerebral aneurysm formation, disruption of blood brain barrier, destabilization of atherosclerotic plaque, hemorrhage transformation after cerebral ischemia." (PMID 29435135, 2018). "Prothrombotic or proinflammatory candidate genes for CP such as TGF-Beta-1, MMP-2, MTFHR-C677T, and TNF-alpha 308, have all been associated with increased cerebrovascular disease risk or worse cerebrovascular disease prognosis." (PMID 24223882, 2013). "Among all MMP subtypes, MMP-2 and MMP-9 are the most studied MMPs in cerebrovascular disease." (PMID 26581247, 2015).
cervical squamous cell carcinoma (3 papers, 2010 to 2024). A squamous cell carcinoma arising from the cervical epithelium. "Low TIMP-2 levels in the blood of squamous cervical cancer patients could indicate more activated MMP-2 and therefore higher usage of TIMP-2, or alternatively, the lower levels could be due to lower production of TIMP-2, leading to less inhibition of MMP-2 activity." (PMID 20671952, 2010).
cervical tumor (3 papers, 2017 to 2022). "In fact, others have observed a correlation between MMP-2 and MMP-9 transcript levels and cervical tumor invasion potential 22,55,56,59." (PMID 30208169, 2018). "Staurosporine (a kinase inhibitor) appears to induce an anti-tumor response in the cervical tumor microenvironment, and inhibits cancer progression and metastases through suppression of MMP-1 and MMP-2." (PMID 29267213, 2017). "Subsequently, we verified the promotional effect of KNTC1 on cervical neoplasm through in-vivo and in-vitro experiments, and speculated that it could mediate tumor invasion via MMP9 and MMP2." (PMID 35389773, 2022). "Moreover, elevated MMP-2 and MT1-MMP protein levels were observed in clinical samples of HPV16-positive invasive cervical tumors when compared to CIN and normal cervical tissues." (PMID 30208169, 2018).
Chagas cardiomyopathy (3 papers, 2014 to 2021). A disease of the cardiac muscle developed subsequent to the initial protozoan infection by trypanosoma cruzi. "In cases of severe Chagas cardiomyopathy MMP‐2 levels added to predictive value of other biomarkers with respect to 1‐year mortality." (PMID 31932967, 2021). "Among MMPs, the gelatinases MMP-2 and MMP-9 have been associated with cardiovascular disorders, including Chagas' cardiomyopathy." (PMID 28118356, 2017). "Whereas MMP-2 seems to be involved in regulation of the immune response, MMP-9 appears to be related to inflammation and development of Chagas cardiomyopathy." (PMID 28118356, 2017). "MMP-2 appears to be related to cardiac-protective and regulatory functions in IND group, while predominance of MMP-9 can be identified as an inflammatory booster, favoring the development of Chagas cardiomyopathy." (PMID 28118356, 2017).
cholestasis (3 papers, 2014 to 2023). Impairment of the bile flow caused by obstruction within the liver, or outside the liver in the bile duct system. "In addition, MMP-2 has been proven to be highly expressed in cholestasis, suggesting that MMP-2 also played an important role in cholestasis." (PMID 37432229, 2023). "Among them, HSP90AA1, TLR4, MMP2, APP, and NFKB1 were the crucial targets of FTA in the treatment of cholestasis." (PMID 37432229, 2023). "More importantly, by combining the outcomes of the PPI network, GO and KEGG analysis, we speculated that FTA could ameliorate cholestasis by acting on important targets such as TRL4, MYD88, NF-KB1, and MMP-2." (PMID 37432229, 2023). "In conclusion, after cholestasis an increase in hepatic ADMA in RL and ML was detected as well as tissue MMP-2 and MMP-9 activation in RL, supporting the evidence of functional heterogeneity among the liver lobes also occurring in an obstructive cholestasis model." (PMID 25013773, 2014).
chronic hepatitis (3 papers, 2013 to 2022). An active inflammatory process affecting the liver for more than six months. "CK-18 M30 and MMP-2 are very interesting markers for chronic hepatitis." (PMID 24032040, 2013).